FGFR2 (fibroblast growth factor receptor 2)
Diseases named in the same sentence as FGFR2 in open-access papers (continued):
Sharing a sentence is not in itself a finding about the gene and the disease.
craniosynostosis (continued). "Both studies reveal midfacial dysgenesis in FGFR2-related craniosynostosis to be a complex phenotype arising from the combined effects of aberrant signaling in multiple craniofacial tissues including cartilage." (PMID 35704354, 2022). "Pivotal component mutations in these pathways, including FGFR2 (fibroblast growth factor receptor 2), TWIST1 (twist, drosophila, homolog of 1) and Axin2 (axis inhibitor 2), have been regarded as the origin of craniosynostosis." (PMID 34134783, 2021). "FGFR2 gene sequencing was performed in six patients with unicoronal or bicoronal craniosynostosis, usually based on clinical and radiological findings, characteristic facial features and hand and foot findings." (PMID 33937142, 2021). "At one or both ages, this population expresses the craniosynostosis-related genes Alpl, Fgfr2, and Fgfr3 as marker genes." (PMID 34880220, 2021). "The suggested genetic causes of craniosynostosis are pathogenic variants in FGFR1, FGFR2, FGFR3, and TWIST1 genes." (PMID 32510873, 2020). "In this study, we describe the main clinical characteristics of 36 patients with craniosynostosis, as well as some of the pathogenic variants of FGFR1, FGFR2, FGFR3, and TWIST1 genes." (PMID 32510873, 2020). "Midfacial dysgenesis can be severe but is variable within and across FGFR2-related craniosynostosis syndromes." (PMID 31064775, 2019). "The findings of this study demonstrate that the 3D dysmorphology of hemimandibles of three FGFR2-related mouse models for craniosynostosis syndromes are easily distinguished from the mandibles of their respective unaffected littermates at birth." (PMID 31064775, 2019). "We provide new information about the molecular processes affecting the mandible in FGFR2-related craniosynostosis syndromes to improve our understanding of craniofacial dysgenesis and move us closer to therapeutic approaches for patients." (PMID 31064775, 2019). "In fact, the majority of mouse craniosynostosis models resulting from FGF signaling aberrations have been generated using activating mutations in FGF receptors, particularly Fgfr2 and Fgfr3." (PMID 29752281, 2018). "Overall, craniosynostosis affected 2 out of 42 patients in our cohort (5%), who both underwent direct sequencing of FGFR2, FGFR3, FGFR1 and TWIST1, with normal results." (PMID 29093661, 2017). "It has been proposed that Twist1 haploinsufficiency favors the formation of Twist1 homodimers in the osteogenic front of cranial sutures, which results in the upregulation of Fgfr2 expression and leads to craniosynostosis." (PMID 24971743, 2014). "Because craniosynostosis typically occurs during fetal life, the safety and effectiveness of FGFR2-based treatment must be tested and an appropriate administration technique should be established using animal experiments in vivo." (PMID 25003957, 2014). "It was found that the mutations in FGF receptors FGFR1, FGFR2, and FGFR3 in humans are associated with craniosynostosis, a characteristic phenotype of the Saethre-Chotzen Syndrome caused by dominant loss-of-function TWIST1 mutations." (PMID 24971743, 2014). "Genes encoding three members of the fibroblast growth factor receptor family (FGFR1, FGFR2 and FGFR3) are commonly mutated in individuals with craniosynostosis." (PMID 25174698, 2014). "Hajihosseini and colleagues reported that mice with heterozygotic abrogation of Fgfr2-exon 9 (IIIc) exhibit craniosynostosis and that Fgfr2IIIb is strongly expressed in calvarial sutures." (PMID 25003957, 2014). "This characteristic distinguishes AS from other FGFR2-related syndromic craniosynostosis, such as CS." (PMID 23593218, 2013).
craniosynostosis (continued). "A prescreen for mutations in the craniosynostosis genes FGFR1, FGFR2, FGFR3, and TWIST was performed and mutations identified in approximately 50% of cases (B. Wollnik, pers." (PMID 24498618, 2013). "Of all the craniosynostosis patients with genetic diagnosis, 32% have mutation in the FGFR2 (Fibroblast Growth Factor Receptor 2) gene." (PMID 23593218, 2013). "The most common and well-characterized cases of craniosynostosis have been caused by mutation in the FGFR1 (fibroblast growth factor receptor 1), FGFR2, FGFR3, TWIST and MSX2 (muscle segment homebox 2) genes." (PMID 20108486, 2009). "Interestingly, identical FGFR2 mutations (e.g. C278F, G298P, and C342T) have been found in patients carrying the diagnosis of Crouzon, Pfeiffer, and Jackson-Weiss craniosynostosis syndromes, suggesting that these entities may represent a clinical spectrum with possible genetic modifiers." (PMID 20108486, 2009). "Investigation of FGFR2-linked craniosynostosis is hindered by the lack of appropriate in vitro models." (PMID 40843495, 2025). "Germline pathogenic FGFR2 variants are typically associated with syndromic craniosynostosis, conditions not characterized by bone fragility or osteoporosis." (PMID 40362441, 2025). "Currently, investigation of the etiology of FGFR2-linked craniosynostosis is hindered by the lack of appropriate in vitro disease models that can properly mimic the disease." (PMID 40843495, 2025). "Overall, neither the 75 kb duplication, nor the 160 kb deletion, is likely to impact the results on FGFR2 observed in the data and in association with craniosynostosis." (PMID 40843495, 2025). "Remarkably, neither short stature nor craniosynostosis was discernible in the patient or among family members, thus negating the possibility of other syndromes linked to FGFR2 mutations and craniosynostosis." (PMID 38909058, 2024). "In addition, other craniosynostosis syndromes, including Jackson-Weiss syndrome and Crouzon syndrome, are also caused by gain-of-function mutations in the D2-D3 linker region of FGFR1 or FGFR2 in a ligand-dependent or independent manner." (PMID 37325554, 2023). "Although the evidence available today is still sparse, recent data unravelled a potential role of FGFR2 on neurodevelopment, such as the reported presumed loss-of-function mutation (c.A1295G) of FGFR2 in an autistic child, without features of craniosynostosis." (PMID 37733178, 2023). "Targeted PCR and Sanger sequencing of FGFR1, FGFR2, FGFR3, TWIST1, and TCF12 genes resulted in the highest diagnostic rate in our cohort of craniosynostosis patients strongly recommend analysing those genes first (isolated CS and syndromic CS without intellectual disability)." (PMID 35591945, 2022). "Likewise the nsSNPs of FGFR2, rs121918506 (Glu565Ala) has reported in Pfeiffer syndrome and craniosynostosis syndrome; and rs121918509 (Ala628Thr, Ala629Thr) has found in LADD syndrome." (PMID 34714320, 2021). "Crouzon syndrome is the most common of the FGFR2 craniosynostosis syndromes." (PMID 32916911, 2020). "Thus, the goal of this study was to describe the major clinical features associated with craniosynostosis, as well as to identify the frequency of pathogenic variants in FGFR1, FGFR2, FGFR3, and TWIST1 in a sample of Mexican patients." (PMID 32510873, 2020). "The vast majority of mutations that cause craniosynostosis syndromes are associated with the FGFR2, which cause quite variable and non-specific phenotypes." (PMID 28129408, 2017). "Since mice in the two groups used in this comparison do not carry an activated FGFR2 mutation associated with craniosynostosis, this comparison reveals differences in associations between brain and skull due to mouse strain/stock." (PMID 28790902, 2017).
craniosynostosis (continued). "The FGFR-related craniosynostosis spectrum includes PS, Apert syndrome, Jackson-Weiss syndrome, Beare-Stevenson syndrome, Crouzon syndrome, Crouzon syndrome with acanthosis nigricans, Muenke syndrome, and FGFR2-related isolated coronal synostosis." (PMID 25129254, 2015). "Our main objective was to determine whether Twist1, FGFR1, FGFR2, or FGFR3 were the sites of causative mutation within our rabbit model of craniosynostosis." (PMID 23738319, 2013). "The current study indicates that this rabbit model of nonsyndromic craniosynostosis likely does not devolve from any other mutation outside of the FGFR2 coding region and extends this same conclusion to FGFR1 and Twist1." (PMID 23738319, 2013). "Notably, mineralization defects and long-bone deformities are indeed hallmarks of Bent Bone Dysplasia (OMIM #614592), a lethal FGFR2-related disease characterized by high perinatal lethality, bent long bones, osteopenia, craniosynostosis, and dysmorphic facial features." (PMID 40362441, 2025). "However, upon a detailed analysis of the clinical features associated with this condition, it emerged that her other peculiar sign, namely xerosis cutis, is not part of the well-established characteristics of FGFR2-associated craniosynostosis." (PMID 36360260, 2022). "A further FGFR2 missense mutation affecting another residue of the third immunoglobulin-like domain was detected in one Pfeiffer syndrome family in which two members had craniosynostosis without limb anomalies." (PMID 28768473, 2017). "Therefore, it is not surprising that most FGFR2 pathogenic variants (mainly missense ones) lead to syndromic craniosynostosis (i.e., Crouzon, Apert, Pfeiffer, Beare-Stevenson cutis gyrate, Jackson-Weiss, and Seathre-Chotzen-like syndromes) with a multisystemic involvement." (PMID 37733178, 2023). "The presence of craniosynostosis had already been investigated through the analysis of the FGFR3 and the FGFR2, the result was normal." (PMID 31578813, 2020). "Perhaps more promising as potential therapies, both RNA interference of FGFR2 and pharmacological inhibition of MEK-ERK signalling have been shown to prevent abnormal skeletal phenotypes in a mouse model of craniosynostosis and reduce cranial suture fusion." (PMID 26635999, 2015). "Our data show that the identified SNPs in FGFR1, FGFR2, and Twist1 all segregated independently of the craniosynostotic phenotype, and therefore a mutation within these genes is highly unlikely to be the causative agent of the craniosynostosis within our model." (PMID 23738319, 2013). "Mutations in the genes encoding fibroblast growth factor receptors 1, 2 and 3 (FGFR-1, FGFR-2, FGFR-3), TWIST and MSX2 (muscle segment homebox 2) have been identified in certain syndromic craniosynostosis." (PMID 20108486, 2009). "On the other hand, the influence of Fgfr2 on craniosynostosis is observed in C57BL/6, but not in BALB/c genetic background." (PMID 37600780, 2023). "The craniosynostosis panel had included FGFR2, but not the critical exon, and the missed WES diagnosis was due to a failure of the variant caller despite good sequencing coverage, which has been subsequently addressed." (PMID 35970915, 2022).
craniosynostosis (continued). "DNA analysis for a specific craniosynostosis syndrome was performed, and no pathogenic variants were found in the FGFR1 (OMIM #136350), FGFR2 (OMIM #176943), FGFR3 (OMIM #134934), and TWIST (OMIM #601622) genes." (PMID 34733861, 2021). "Activating mutations in Fibroblast Growth Factor Receptor 2 (Fgfr2) and inactivating mutations in Alpl, the gene for tissue nonspecific alkaline phosphatase (TNAP) can cause craniosynostosis." (PMID 32470062, 2020). "Previous mandibular analyses in mouse models for craniosynostosis include little or no quantitative or gene expression information for embryonic and newborn mice, although it has been reported that Fgfr2 is expressed in mandibular osteoblasts." (PMID 31064775, 2019). "To date, we have tested, by dideoxy‐sequencing of TCF12, 105 Dutch syndromic and nonsyndromic coronal craniosynostosis index patients with negative results for FGFR2, FGFR3, and TWIST1 testing." (PMID 27158814, 2016). "However, we cannot rule out an interaction of these genes with FGFR2 in craniosynostosis on the basis of our current observations." (PMID 40843495, 2025). "Furthermore, FGFR2 p.Cys342Arg enhanced oxidative phosphorylation and converted mitochondrial fusion to the fission of MC3T3-E1, promoting osteogenic differentiation and craniosynostosis in Crouzon syndrome." (PMID 36231091, 2022). "Lastly, in order to determine whether aberrant regulation of genes known to be involved in the aetiology of craniosynostosis underpinned any of the defects we observed, we examined the expression of Noggin, FGFR1/pFGFR1, FGFR2, Runx2 and Twist1 by immunohistochemistry." (PMID 27756203, 2016).
Apert syndrome (109 papers, 2003 to 2026). "In Apert syndrome, in the vast majority of cases there are one of two mutations in the gene for FGFR2." (PMID 40894678, 2025). "These unresolved questions are closely tied to the pathological mechanisms underlying Apert syndrome, which center on dysregulated FGFR2 signaling." (PMID 41268110, 2025). "Nearly 100% of all cases of Apert syndrome are caused by one of two FGFR2 mutations and result in coronal suture fusion prior to birth." (PMID 39984434, 2025). "Apert syndrome is a rare, congenital, autosomal dominant disorder caused by a mutation in the fibroblast growth factor receptor 2 (FGFR2) gene, seen in one in 65,000 births." (PMID 40443603, 2025). "The previous disease exhibits considerable overlap with Pfeiffer syndrome (MIM #101600) related to FGFR1 (MIM *136350) and FGFR2 variants and Apert syndrome (MIM #101200) related to FGFR2 variants." (PMID 40673520, 2025). "Activating mutations of FGFR2 lead to Apert syndrome, Pfeiffer syndrome, Antley–Bixler syndrome and Beare–Stevenson syndrome, which are associated with hydroureter, unilateral renal aplasia and/or vesicoureteral reflux, with conductive hearing loss." (PMID 38353121, 2024). "Fetuses born with Apert syndrome, a syndrome associated with the premature closure of the coronal suture due to mutations in the FGFR2 gene, display deformities in the temporal lobe." (PMID 39735065, 2024). "When examining variants within the FGF and FGFR genes, the FASD cohort was found to be enriched in the A allele of rs147057 in FGFR2, which has been found in a patient with Apert syndrome." (PMID 38785976, 2024). "Apert syndrome is a severe autosomal dominant disorder caused by gene mutations that encode fibroblast growth factor receptor 2 (FGFR2) on chromosome 10q." (PMID 39061616, 2024). "Apert syndrome is a rare genetic craniosynostosis disorder (acrocephalosyndactyly type I) caused by FGFR2 gene mutations." (PMID 38929327, 2024). "In cases of Apert syndrome, the medical team requires the involvement of a medical geneticist to establish the FGFR2 mutation; the definitive diagnosis can be confirmed only by molecular testing." (PMID 39061616, 2024). "Individuals with Apert syndrome, due to mutations in the FGFR2 gene, present temporal lobe abnormalities." (PMID 39735065, 2024). "Nevertheless, mSSCs can be generated that express the Apert syndrome FGFR2 mutation, and these mSSCs have increased competitiveness in in vitro models, as well as after transplantation." (PMID 39459551, 2024). "Conditions such as achondroplasia and Apert syndrome, are known to be induced by single point mutations in fibroblast growth factor receptors (FGFRs): FGFR2, in the case of Apert syndrome, and FGFR3, in the case of achondroplasia." (PMID 37568254, 2023).